ACYP2 (acylphosphatase 2)
Description:
catalyzes the hydrolysis of acylphosphates compounds containing a carboxylphosphate bond.
Synonyms: ACYP; ACYM
Tractability: PROTAC: ubiquitination databases record sites on it; its protein half-life has been measured.
Safety:
Unwanted effects reported when the protein is acted on. In parentheses: how it was acted on, where the effect was seen, and who reports it.
ototoxicity (source: ClinPGx)
Gene: Protein-coding gene on chromosome 2 (53,970,838 to 54,305,300, forward strand). Ensembl gene ENSG00000170634.
Subcellular location (Human Protein Atlas): Nucleoplasm
Gene Ontology:
Molecular function: acylphosphatase activity; identical protein binding; protein binding
Biological process: phosphate-containing compound metabolic process
Cellular component: mitochondrion
Genetic constraint (gnomAD): Loss-of-function variants: 3 observed, 3.91 expected, observed/expected ratio (o/e) 0.77, 90% interval 0.34 to 1.73. That is too few expected variants to judge how well the gene tolerates losing a copy. Missense variants: 86 observed, 76.24 expected, observed/expected ratio (o/e) 1.13, 90% interval 0.95 to 1.35. Synonymous variants: 31 observed, 25.65 expected, observed/expected ratio (o/e) 1.21, 90% interval 0.91 to 1.63.
Homologues: Orthologues: macaque ACYP2 (97% identical), pig ACYP2 (96% identical), chimpanzee ACYP2 (87% identical), mouse Acyp2 (84% identical), tropical clawed frog acyp2 (80% identical), guinea pig ACYP2 (75% identical), dog ACYP2 (58% identical), rat Acyp2 (57% identical), zebrafish acyp2 (42% identical). Paralogues in human: ACYP1 (57% identical).
Diseases named in the same sentence as ACYP2 in open-access papers:
ACYP2 is named in the same sentence as 40 diseases in open-access papers, as found by Europe PMC text mining. Sharing a sentence is not in itself a finding about the gene and the disease. The quoted sentences say what the papers report.
coronary heart disease (6 papers, 2016 to 2024). "The rs11125529, rs7675998, rs8105767, and rs7194734 SNPs belong to the ACYP2, NAF1, ZNF208, and MPHOSPH6 genes, respectively, which were found to be associated with increasing risk of developing coronary heart disease." (PMID 38293941, 2024). "Previously, several studies have reported the association between ACYP2 gene and some other diseases, such as lung cancer, colorectal cancer (CRC), high altitude pulmonary edema (HAPE) and coronary heart disease (CHD)." (PMID 29228661, 2017). "A recent paper has indicated a significant association between ACYP2 and TSPYL6 single nucleotide polymorphisms (SNPs) associated with coronary heart disease (CHD)." (PMID 29228661, 2017). "A recent genome-wide meta-analysis showed that ACYP2 rs11125529 affects telomere length and coronary heart disease in the Chinese Han population." (PMID 27974682, 2016). "Furthermore, genome-wide association studies of adult leukocyte TL (LTL) identified 7 single-nucleotide variations (ACYP2, NAF1, OBFC1, RTEL1, TERC, TERT, ZNF208) linked with LTL that mutually project towards an increased risk for coronary artery disease." (PMID 35930283, 2022).
glioma (4 papers, 2015 to 2022). A benign or malignant brain and spinal cord tumor that arises from glial cells (astrocytes, oligodendrocytes, ependymal cells). "First, we demonstrated that ACYP2 was significantly elevated in glioma tissues in comparison with control subjects, and found a significant association of increased expression of ACYP2 with poor survival in low-grade glioma patients." (PMID 32517717, 2020). "In this study, we observe that ACYP2 is significantly upregulated in gliomas, and find a significant association of increased expression of ACYP2 with poor patient survival in low-grade glioma patients." (PMID 32517717, 2020). "In summary, we find that increased expression of ACYP2 is frequently found in gliomas, and closely associated with poor patient survival." (PMID 32517717, 2020). "To reveal molecular mechanisms underlying oncogenic role of ACYP2 in glioma cells, we first tested the effect of ACYP2 on intracellular Ca2+ concentration." (PMID 32517717, 2020). "Considering the relatively poor specificity of calpain, we speculate that ACYP2 may act on some key transcription factors associated with malignant progression of glioma through regulating Ca2+/calpain signaling." (PMID 32517717, 2020). "For example, ACYP2 was reported to contribute to the malignant progression of glioma by promoting Ca2+ efflux and the subsequent activation of c-Myc and STAT3 signals." (PMID 36147313, 2022). "Mechanistically, ACYP2 promoted malignant progression of glioma cells through regulating intracellular Ca2+ homeostasis via its interaction with PMCA4, thereby activating c-Myc and PTP1B/STAT3 signals." (PMID 32517717, 2020). "To better understand biological role of ACYP2 in glioma, we first tested its effect on intracellular Ca2+ homeostasis in glioma cells." (PMID 32517717, 2020). "A series of in vitro experiments were performed to determine biological role of ACYP2 in malignant phenotypes of glioma cells." (PMID 32517717, 2020). "Next, we attempted to determine the potential role of c-Myc in oncogenic function of ACYP2 in glioma cells." (PMID 32517717, 2020). "A series of in vitro and in vivo functional studies demonstrate that ACYP2 is a potent oncogene in glioma cells through promoting Ca2+ efflux and subsequently activating c-Myc and STAT3 signals." (PMID 32517717, 2020). "Collectively, these findings further support oncogenic role of ACYP2 in glioma cells by modulating intracellular Ca2+ homeostasis." (PMID 32517717, 2020). "ACYP2 expression was significantly elevated in glioma tissues in comparison with control subjects at both mRNA and protein levels." (PMID 32517717, 2020). "On the other hand, ectopic expression of ACYP2 dramatically promoted malignant phenotypes of glioma cells, further supporting its oncogenic function." (PMID 32517717, 2020). "Functional studies demonstrate that ACYP2 acts as an oncogenic function in glioma cells through regulating intracellular Ca2+ homeostasis and subsequently activating c-Myc and STAT3 signals." (PMID 32517717, 2020). "To prove this, we examined c-Myc levels in glioma cells ectopically expressing or knocking down ACYP2 by western blot using antibody against C terminus of c-Myc (9E10), which recognizes only full-length c-Myc." (PMID 32517717, 2020). "In the present study, we find that ACYP2 functions as an oncogene in glioma cells through the interaction with PMCA4." (PMID 32517717, 2020). "Conversely, ectopic expression of ACYP2 in glioma cells dramatically promoted malignant phenotypes of glioma cells." (PMID 32517717, 2020). "The functions of ACYP2 in glioma cells were determined by a series of in vitro and in vivo experiments, including cell proliferation, colony formation, cell cycle, apoptosis, migration, invasion and nude mouse tumorigenicity assays." (PMID 32517717, 2020). "We first examined mRNA and protein expression of ACYP2 in 52 gliomas and 24 normal brain tissues (control subjects) by qRT-PCR, immunohistochemistry and western blot assays." (PMID 32517717, 2020).
glioma (continued). "Knocking down ACYP2 in glioma cells significantly inhibited cell proliferation, colony formation, migration, invasion and tumorigenic potential in nude mice, and induced cell cycle arrest and apoptosis." (PMID 32517717, 2020). "Taken together, these data support the oncogenic role of ACYP2 in glioma cells." (PMID 32517717, 2020). "Thus, we suppose that ACYP2 promotes malignant progression of glioma through modulating the activity of Ca2 + −dependent calpains." (PMID 32517717, 2020). "In this study, we provided strong evidence supporting that ACYP2 is a potent oncogene in glioma." (PMID 32517717, 2020). "The effect of ACYP2 on cell migration and invasion was next assessed in three glioma cell liens." (PMID 32517717, 2020). "The results showed that promoting effect of ACYP2 on glioma cell proliferation could be partially reversed by the treatment of c-Myc inhibitor 10,058-F4." (PMID 32517717, 2020). "Thus, we speculate that ACYP2/Ca2+/calpain signaling axis may act on some key transcription factors and affect their activity, thereby contributing to malignant phenotypes of glioma cells." (PMID 32517717, 2020). "In addition, we also tested the effect of ACYP2 depletion on the apoptosis of glioma cells." (PMID 32517717, 2020). "Our data demonstrate that ACYP2 functions as an oncogene in glioma through activating c-Myc and STAT3 signals via the regulation of intracellular Ca2+ homeostasis, and indicate that ACYP2 may be a potential therapeutic target and prognostic biomarker in gliomas." (PMID 32517717, 2020). "To determine the role of intracellular Ca2+ homeostasis in tumor-promoting effect of ACYP2, we treated glioma cells with a highly selective Ca2+ chelator BAPTA-AM, and demonstrated that Ca2+ chelation could effectively reverse inhibitory effect of ACYP2 depletion on cell proliferation and migration." (PMID 32517717, 2020). "Thus, we suppose that ACYP2 may promote phosphorylation and activity of STAT3 through modulating Ca2+/calpain signaling axis, contributing to malignant progression of glioma cells." (PMID 32517717, 2020).
ischemic stroke (3 papers, 2017 to 2019). A stroke disorder caused by obstruction of blood flow to the brain, due to thrombotic (local blood clot formation) or embolic (due to a blood clot or other material traveling from another site) event. "Genome wide association study have demonstrated that genetic polymorphisms in ACYP2 are associated with telomere length, which has led to studies of the association between ACYP2 and various diseases, including ischemic stroke." (PMID 29228661, 2017). "The rs11896604 and rs17045754 loci on the ACYP2 gene were found to be associated with ischemic stroke in a case-control study of 300 patients with ischemic stroke and 300 healthy individuals." (PMID 28424424, 2017).
liver cancer (3 papers, 2017 to 2022). An epithelial or non-epithelial malignant neoplasm that arises from the liver. "We explored the association between single nucleotide polymorphisms (SNPs) in ACYP2 and liver cancer risk." (PMID 28978066, 2017). "We evaluated the relationships between 13 SNPs in ACYP2 and the risk of liver cancer in a Han Chinese population." (PMID 28978066, 2017). "Moreover, ACYP2 gene polymorphism was associated with the risk of cirrhosis developing into liver cancer, and high ACYP2 expression was associated with better overall survival in HCC, which indicated its important role in HCC progression." (PMID 36147313, 2022). "ACYP2 gene, located on chromosome 2p16.2, encodes small cytosolic acylphosphatase enzyme, and publication have explored the association between ACYP2 polymorphisms liver cancer risk." (PMID 29156773, 2017). "We hypothesized that genetic variations in ACYP2 could influence susceptibility to liver cancer." (PMID 28978066, 2017). "Therefore, ACYP2 polymorphisms may contribute to liver cancer through impacting telomere length." (PMID 28978066, 2017). "However, a direct association between single nucleotide polymorphisms (SNPs) in ACYP2 and susceptibility to liver cancer has not been established." (PMID 28978066, 2017).
lung carcinoma (3 papers, 2012 to 2017). "In sum, we have identified several novel associations between three SNPs in ACYP2 (rs1682111, rs11896604 and rs843720) and lung cancer in the Chinese Han population." (PMID 27974682, 2016). "As far as we know, no studies have investigated the correlations between SNPs in ACYP2 and lung cancer susceptibility." (PMID 27974682, 2016). "Single nucleotide polymorphisms (SNPs) in the telomere-associated gene ACYP2 are associated with increased lung cancer risk." (PMID 27974682, 2016). "We explored the correlation between ACYP2 SNPs and lung cancer susceptibility in the Chinese Han population." (PMID 27974682, 2016). "Those issues will be addressed in future studies, along with further characterization of the molecular mechanism underlying the association of ACYP2 SNPs and lung cancer and prospective studies to validate their clinical utility." (PMID 27974682, 2016). "Thus three SNPs in ACYP2 (rs1682111, rs11896604 and rs843720) associate with lung cancer in the Chinese Han population." (PMID 27974682, 2016). "We therefore performed a case-control association study to determine whether any of 13 SNPs in the ACYP2 gene are associated with lung cancer susceptibility in the Chinese Han population." (PMID 27974682, 2016). "However, the mechanism by which ACYP2 contributes to lung cancer will need to be explored in future studies." (PMID 27974682, 2016). "First, we present no data on the relation between ACYP2 SNPs and the most influential lung cancer risk: smoking." (PMID 27974682, 2016). "Our findings suggest ACYP2 may be a useful marker that informs clinical decisions, and may shed light on new candidate genes and new ideas about the mechanism governing the occurrence of lung cancer." (PMID 27974682, 2016). "ACYP2 (OR = 0.08, p<0.0001), also within this TOH, is under-expressed in ever-smokers associated with decreased lung-cancer-risk, but its differential expression is not germane in never-smokers." (PMID 22384118, 2012).
brain tumors (2 papers, 2020 to 2022). "An illustrative example is the association between ACYP2 and ototoxicity in patients with pediatric brain tumors which was identified in a genome-wide association study (GWAS)." (PMID 36536332, 2022). "The acylphosphatase 2 (ACYP2) rs1872328 was reported first in children with brain tumors and was then confirmed in patients with HGOS." (PMID 32629971, 2020).
breast carcinoma (2 papers, 2016 to 2020). "We performed a case-control study to investigate the associations between seven single nucleotide polymorphisms (SNPs) in the acylphosphatase 2 (ACYP2) gene and breast cancer (BC) risk in a Han Chinese population." (PMID 27894080, 2016).
deafness (2 papers, 2018 to 2023). An inherited or acquired condition characterized by the complete loss of the ability to hear from one or both ears. "Genome-wide studies have described SNVs in acylphosphatase 2 (ACYP2), involved in calcium homeostasis and Mendelian deafness WFS1 genes, as predictors of CDDP-induced ototoxicity." (PMID 36980643, 2023). "We did not include the SNPs in the following genes: ACYP2 (coding for an acylphosphatase), SLC31A1 gene coding for the copper transport protein 1, SLC22A2 coding for the organic cation transport protein 2, megalin, TPMT and COMT and Mendelian deafness gene." (PMID 30112115, 2018).
esophageal cancer (2 papers, 2017 to 2019). A primary or metastatic malignant neoplasm involving the esophagus. "In our research, we also found that rs11896604 and rs17045754 loci on ACYP2 gene increased the esophageal carcinoma risk." (PMID 28424424, 2017). "We adopted case-control method to explore the influence of ACYP2 genetic polymorphisms on esophageal carcinoma." (PMID 28424424, 2017). "So the association between ACYP2 gene polymorphisms and drinking and smoking status in esophageal carcinoma need to be evaluated in future studies." (PMID 28424424, 2017). "In our study, we found that ACYP2 rs11125529 increased the risk of esophageal cancer." (PMID 28424424, 2017). "So, we want to examined whether the ACYP2 gene polymorphism have impact on the risk of esophageal carcinoma in Chinese population." (PMID 28424424, 2017). "In summary, this study results provided new evidence that ACYP2 gene was associated with esophageal carcinoma in the Chinese Han population from northwest China, which may serve as a prognostic biomarker for esophageal carcinoma among Chinese population." (PMID 28424424, 2017). "In conclusion, ACYP2 gene may be associated with an increased risk of esophageal carcinoma in Chinese Han populations." (PMID 28424424, 2017). "Therefore, we investigated whether ACYP2 polymorphisms have impact on the risk of esophageal carcinoma in Chinese." (PMID 28424424, 2017). "However, the role of ACYP2 genetic variants on esophageal carcinoma susceptibility is still unknown." (PMID 28424424, 2017). "So, we assume that ACYP2 gene affecting the incidence of esophageal cancer through impact the telomere length." (PMID 28424424, 2017). "However, the role of ACYP2 gene on esophageal carcinoma susceptibility is still unknown." (PMID 28424424, 2017). "Future study will focus on the function of ACYP2 in esophageal carcinoma patients, leading to the better prevention or early detection and better prognosis for esophageal carcinoma." (PMID 28424424, 2017).
gastric cancer (2 papers, 2016 to 2017). A primary or metastatic malignant neoplasm involving the stomach. "We found a possible association between ACYP2 gene and the risk of gastric cancer by reviewing the literatures." (PMID 28415712, 2017).
hearing loss (2 papers, 2017 to 2019). "Besides, another two studies suggested a significant association between rs1872328 of ACYP2 gene and susceptibility to cisplatin-induced hearing loss." (PMID 29228661, 2017). "Genetic variants in acylphosphatase 2 (ACYP2) and Wolframin ER transmembrane glycoprotein (WFS1) were identified as predictive markers for hearing loss." (PMID 30999660, 2019). "We could confirm the association between a genetic variant in ACYP2 and clinical reported hearing loss, but not with tone audiometrical measurements." (PMID 30999660, 2019).
osteosarcoma (2 papers, 2016 to 2020). A usually aggressive malignant bone-forming mesenchymal neoplasm, predominantly affecting adolescents and young adults. "A genetic variant (rs1872328) in Acylphosphatase 2 (ACYP2), coding for a protein thought to be responsible for hair cell development, was found to be significantly associated with hearing loss in pediatric patients treated with cisplatin for embryonal tumors and osteosarcomas." (PMID 32848787, 2020).
ototoxicity (2 papers, 2015 to 2019). damage to the ear, specifically the cochlea or auditory nerve as a result of some toxic stimulus, eg from a drug. "The initial studies of Xu and Vos reported that the A allele of the genetic variants rs1872328 in the ACYP2 gene was only present in patients with ototoxicity, i.e., 13.8% and 6.5%, respectively, carried the A allele." (PMID 30999660, 2019). "Therefore, even if the ACYP2 SNPs were genotyped, this study was likely underpowered to confirm the reported association with treatment-related ototoxicity." (PMID 26400460, 2015).
pulmonary edema (2 papers, 2016 to 2017). Accumulation of fluid in the lung tissues causing disturbance of the gas exchange that may lead to respiratory failure. "In a study of ACYP2 and high-altitude pulmonary edema, two sites, rs11896604 and rs12615793, were found to reduce the risk of high-altitude pulmonary edema." (PMID 28424424, 2017).
erythroleukemia (1 paper, 2020). Acute erythroid leukemia characterised by the presence of at least 50% erythroid precursors and at least 20% myeloblasts in the bone marrow. "In addition, ACYP has also been proven to be involved in differentiation of human erythroleukemia K562 cell line, and ectopic expression of ACYP2 can induce cell apoptosis in HeLa cells." (PMID 32517717, 2020).
glioblastoma (1 paper, 2020). The most malignant astrocytic tumor (WHO grade IV). "Next, through analyzing the Cancer Genome Atlas (TCGA) dataset, we found that increased expression of ACYP2 was clearly associated with poor survival in low-grade glioma (LGG) patients (HR =0.23 with log-rank P < 0.0001), but not in glioblastoma (GBM) patients (data not shown)." (PMID 32517717, 2020).
Stroke (1 paper, 2017). Sudden impairment of blood flow to a part of the brain due to occlusion or rupture of an artery to the brain. "Genetic polymorphisms of telomere-related genes such as ACYP2, TSPYL6, and TERT have been reported to be associated with stroke." (PMID 29383136, 2017).